MIR556 (microRNA 556)
Synonyms: hsa-mir-556; MIRN556; mir-556
Gene: MicroRNA gene on chromosome 1 (162,342,546 to 162,342,640, forward strand). Ensembl gene ENSG00000207729.
Gene Ontology:
Biological process: miRNA-mediated post-transcriptional gene silencing
Cellular component: RISC complex
Homologues: Orthologues: chimpanzee ptr-mir-556 (100% identical), macaque MIR556 (72% identical).